RAD51-AS1 (RAD51 antisense RNA 1)
Synonyms: TODRA
Gene: Long non-coding RNA gene on chromosome 15 (40,686,161 to 40,695,128, reverse strand). Ensembl gene ENSG00000245849.
Diseases named in the same sentence as RAD51-AS1 in open-access papers:
RAD51-AS1 is named in the same sentence as 4 diseases in open-access papers, as found by Europe PMC text mining. Sharing a sentence is not in itself a finding about the gene and the disease. The quoted sentences say what the papers report.
breast carcinoma (2 papers, 2015 to 2017). "Long non-coding RNA RAD51 antisense RNA 1 (RAD51-AS1, also known as TODRA) has been shown to be down-regulated by E2F1, a key cell cycle and apoptosis regulator, in breast cancer." (PMID 28667302, 2017).
ovarian carcinoma (1 paper, 2024). A malignant neoplasm originating from the surface ovarian epithelium. "The present study aims to determine the molecular mechanism mediated by RAD51 antisense RNA 1 (RAD51-AS1) in ovarian cancer (OvCA)." (PMID 38584230, 2024).
RAD51-AS1 also shares sentences with these, for which no sentence is quoted: breast tumors (1 paper); cancer (1).